IGF1 (insulin like growth factor 1)
Diseases named in the same sentence as IGF1 in open-access papers (continued):
Sharing a sentence is not in itself a finding about the gene and the disease.
rheumatic diseases (4 papers, 2017 to 2024). "Collectively, these results suggested that the effect of TG on the TNF‐a‐induced rheumatism cell model was impeded by Lnc‐ENST00000602558, as indicated increased IGF1 levels and the induced production of pro‐inflammatory cytokines." (PMID 38270302, 2024). "Children and adolescents with rheumatic diseases need to be periodically checked with hormonal analysis of FSH, LH, IGF-1, ACTH, and cortisol." (PMID 37685999, 2023).
Skin ulcer (4 papers, 2016 to 2021). A discontinuity of the skin exhibiting complete loss of the epidermis and often portions of the dermis and even subcutaneous fat. "In contrast, Gong and co-workers explored the effects of exogenous IGF-1 on the healing process of skin ulcers in diabetic male rats." (PMID 34502429, 2021). "The study results reported that IGF-1 promotes the wound healing of skin ulcers in diabetic rats." (PMID 34502429, 2021).
soft tissue sarcoma (4 papers, 2015 to 2025). A malignant neoplasm arising from muscle tissue, adipose tissue, blood vessels, fibrous tissue, or other supportive tissues excluding the bones. "Pediatric bone and soft tissue sarcomas often display increased Akt phosphorylation through up regulation of insulin-like growth factor (IGF1) signaling." (PMID 26402468, 2015).
tendinitis (4 papers, 2012 to 2023). Inflammation of a tendon, usually resulting from an overuse injury. "In tendinitis repair, shockwaves increase transforming growth factor beta 1 (TGFβ1) and insulin-like growth factor 1 (IGF-1)." (PMID 31936603, 2020). "Another equine flexor tendon model for tendonitis compared MSCs, MSCs with insulin-like growth factor-1 (IGF-1) gene-enhanced MSCs, and controls." (PMID 25098364, 2012).
ulcer (4 papers, 2019 to 2022). "To determine the protective mechanism of KFX against WIRS-induced ulcer rats, we tested the IGF-1/Akt signalling related protein expression." (PMID 31696757, 2019). "Moreover, PGE significantly downregulated the increased COX-2, TGF-β, and IGF-1 relative gene expressions, confirming its beneficial effect in ulcer healing." (PMID 35883720, 2022). "Due to the cross‐sectional nature of the study, we also could not determine if or how IGF‐1 levels change before and after the appearance of an ulcer, although total IGF‐1 does not typically undergo rapid fluctuations." (PMID 31249708, 2019).
uterine serous carcinoma (4 papers, 2013 to 2023). "In OC mice models, metformin treatment decreases IGF-1 levels and the IGF-1 signaling pathway in uterine serous carcinoma." (PMID 38203494, 2023). "Like progestins, metformin also inhibits the insulin/IGF-1 pathway, allowing metformin to be pro-apoptotic in uterine serous carcinoma." (PMID 28698465, 2017).
visceral leishmaniasis (4 papers, 2014 to 2021). A severe form of leishmaniasis characterized by irregular bouts of fever, substantial weight loss, swelling of the spleen and liver, and anemia (which may be serious). "In a hamster model of visceral leishmaniasis (VL), Osorio and colleagues showed that Leishmania donovani infected macrophages displayed enhanced STAT6 and STAT3 signalling in response to the growth factors FGF2 and IGF1, further enhanced by co-stimulation with IL-4 or IL-10." (PMID 29352310, 2018).
-secreting pituitary adenoma (3 papers, 2007 to 2022). "Growth hormone-secreting pituitary adenoma (GHPA) is an insidious disease with persistent hypersecretion of growth hormone and insulin-like growth factor 1, causing increased morbidity and mortality." (PMID 35947334, 2022).
acute leukemia (3 papers, 2015 to 2024). A clonal (malignant) hematopoietic disorder with an acute onset, affecting the bone marrow and the peripheral blood. "This study investigated bone mineral deficits in children who survived childhood acute leukemia and analyzed the association of the insulin-like growth factor-1 (IGF-1) level with bone mineral density (BMD) status." (PMID 38610974, 2024). "In this study, we investigated bone mineral deficits in children who survived childhood acute leukemia and explored the association between the insulin-like growth factor-1 (IGF-1) level and bone mineral density (BMD)." (PMID 38610974, 2024). "Targeting the GH/IGF-1 axis to ensure optimal skeletal health in children, especially in those who survive acute leukemia, is important." (PMID 38610974, 2024). "Therefore, this study investigated the relationship between serum IGF-1 levels and BMD and evaluated the effectiveness of IGF-1 as an indicator of bone health in survivors of childhood acute leukemia." (PMID 38610974, 2024). "Although the association between serum IGF-1 levels and BMD is debatable, our study results show that serum IGF-1 levels may serve as an indicator of bone health status in survivors of childhood acute leukemia." (PMID 38610974, 2024). "The low levels of IGF-1 before HSCT are consistent with previous findings in children with acute leukemia or non-neoplastic hematological diseases." (PMID 34959885, 2021). "However, research on the relationship between serum IGF-1 levels and bone status in survivors of childhood acute leukemia is lacking." (PMID 38610974, 2024).
acute pancreatitis (3 papers, 2011 to 2021). An acute inflammatory process that leads to necrosis of the pancreatic parenchyma. "Igf1, like Igf2, is highly enriched in the mesenchyme-derived cells compared to non-mesenchyme cells and paracrine release of IGF1 from fibroblasts, which derive from the primitive mesenchyme, stimulate acinar cell proliferation during regeneration from acute pancreatitis." (PMID 33057429, 2020). "Moreover, IGF-1 increases regeneration of pancreatic acinar cells following acute pancreatitis." (PMID 24212642, 2011). "Secondly, treatment with growth hormone, IGF-1, and HGF exhibits protective or/and therapeutic effect in experimental acute pancreatitis." (PMID 34638910, 2021). "It has been reported that expression of IGF-1 and TGF-β1 are remarkably upregulated in acute pancreatitis." (PMID 24212642, 2011).
adenomyosis (3 papers, 2020 to 2025). The growth of endometrial tissue inside the muscular wall of the uterine corpus. "Our study revealed that IGF1 was differentially expressed in the microarray analysis and was significantly correlated with expression of METTL3 in the endometrium of adenomyosis patients." (PMID 32719721, 2020). "Thus, increased IGF1 in eutopic endometrium may mediate the regulation of METTL3 and contribute to the endometrial dysfunction in adenomyosis women through EMT." (PMID 32719721, 2020).
Airway obstruction (3 papers, 2012 to 2025). Obstruction of conducting airways of the lung. "First, AT has a proven benefit for sleep quality by reducing airway obstruction, resulting in the enhanced secretion of both growth hormone and insulin-like growth factor-1, which are potent appetite stimulators and anabolic intermediates." (PMID 40150553, 2025).
allergic contact dermatitis (3 papers, 2014 to 2024). An inflammatory skin condition caused by an immune response to direct contact between the skin and an allergen. "Therapeutically relevant delivery of IGF-1 for the treatment of allergic contact dermatitis could be achieved either by continuous systematic delivery of rhIGF-1 through osmotic minipumps or by topical application in hydrogel." (PMID 25056699, 2014).
Alström Syndrome (3 papers, 2008 to 2024). "Free IGF1, IGFBP-1 were significantly reduced and IGFBP-2 was markedly increased in all 3 patients compared to age-matched controls, which points to a growth hormone deficiency (GHD) condition in Alstrom syndrome." (PMID 19128470, 2009).
amenorrhea (3 papers, 2013 to 2024). The absence of menses in a woman who has achieved reproductive age. "Slow growth associated with GH/IGF-1 axis impairment had the longest duration of symptoms, followed by amenorrhea and delayed puberty associated with HPG axis impairment." (PMID 38957439, 2024). "Energy deficits lead to hormonal changes, including decreased insulin-like growth factor-1 (IGF-1), growth hormone (GH) resistance, amenorrhoea, increased cortisol levels, and changes in hunger and satiety signalling (due to decreased levels of leptin, increased peptide YY, and ghrelin resistance)." (PMID 36401318, 2022).
Arthralgia (3 papers, 2021 to 2025). "A study evaluating clinically suspect arthralgia patients determined that IL-7R and IGF-1 were differentially expressed among individuals who did and did not progress to IA." (PMID 34071429, 2021). "While several potential etiologies have been proposed for AI-induced arthralgia, an intriguing possibility involves growth hormone (GH)/insulin-like growth factor 1 (IGF-1) modulation by AI therapy with subsequent development of adverse musculoskeletal effects." (PMID 33910628, 2021).
asphyxia (3 papers, 2020 to 2024). A state of general hypoxia and hypercapnia (abnormally elevated carbon dioxide (CO2) levels in the blood), resulting in acidosis, which affects all tissues in the body. "The results in children and adults report safe profile effects of long-term therapy, although more studies are needed to analyze the effectivity of GH treatment and IGF-1 levels in perinatal asphyxia, and its safety profile in newborns." (PMID 36232848, 2022). "The asphyxia-IGF-1 group had higher PaO2 values than sham controls, albeit within the normal range." (PMID 39507274, 2024). "The changes in the IGF-1 amounts in the nervous tissue after HI might contribute to the resulting white matter disorders, observed in newborn children who experienced perinatal asphyxia." (PMID 32691304, 2020).
ataxia telangiectasia (3 papers, 2014 to 2024). Ataxia-telangiectasia is the association of severe combined immunodeficiency (affecting mainly the humoral immune response) with progressive cerebellar ataxia. "Loss of ATM activity, either by genomic mutation (ATM-deficient fibroblasts from an ataxia telangiectasia patient) or by administration of a chemical inhibitor (AAI, an inhibitor of ATM and ATR), blocks IGF-1-sCLU expression in senescent cells." (PMID 24937130, 2014). "Both types of patients have increased serum IGF-1 and IGFBP-2 levels, and decreased serum IGFBP-1 levels; while only ataxia-telangiectasia patients have high serum insulin levels." (PMID 26331037, 2014). "Two other ataxic diseases with a different aetiology and pathology, ataxia-telangiectasia and Friedreich’s ataxia (FRDA), might also show disturbed IGF-1 function." (PMID 26331037, 2014). "Ataxia-telangiectasia and FRDA show cumulative DNA damage and might also show disturbed IGF-1 function." (PMID 26331037, 2014).
atopic dermatitis (3 papers, 2013 to 2024). "In the logistic regression model, decreased levels of serum estradiol, dehydroepiandrosterone sulfate, FT4, and IGF-1, and increased levels of IGFBP3 were associated with an increased likelihood of exhibiting atopic dermatitis." (PMID 38812645, 2024).
bacterial sepsis (3 papers, 2021 to 2022). "In children with bacterial sepsis and septic shock, GH levels were elevated significantly, which is in contrast to the changes observed in IGF-1 levels." (PMID 34295909, 2021).
bladder urothelial carcinoma (3 papers, 2020 to 2022). "In a previous study, following the analysis results from TCGA database, AHNAK and IGF-1 were selected as independent risk factors associated with the prognosis of patients with bladder urothelial carcinoma." (PMID 36557813, 2022). "It is noteworthy that the receptor of IGF1 is regarded as a classical cancer-promoting molecule in bladder urothelial carcinoma." (PMID 32420368, 2020). "Therefore, whether IGF-1 is a potential prognostic factor in bladder urothelial cancer needs further experimental study." (PMID 32420368, 2020).
Blindness (3 papers, 2010 to 2020). Blindness is the condition of lacking visual perception defined as a profound reduction in visual perception. "Although further studies are required to determine the therapeutic effect of IGF-1 in protecting RGC viability and neurite outgrowth in vivo, our results present IGF-1 as a novel therapeutic strategy for reducing the vision loss and blindness that result from hypoxia-induced retinal cell loss." (PMID 24049436, 2013).
cerebral palsy (3 papers, 2010 to 2020). A group of disorders affecting the development of movement and posture, often accompanied by disturbances of sensation, perception, cognition, and behavior. "Studies on cerebral palsy also proved miR-1 regulation of mRNA encoding BDNF, and it has been also shown that miR-1 prevented apoptosis via Igf1 regulation." (PMID 32283635, 2020).
cerebral small vessel disease (3 papers, 2021 to 2025). Cerebral small vessel disease is the term currently used to pathological processes that affect the brain parenchymal circulation (arterioles, capillaries, and veins). "The main findings of possible mechanism of insulin-like growth factor-1 and cerebral small vessel disease." (PMID 37358957, 2023).
childhood cancers (3 papers, 2012 to 2024). "IGF-1 status should be monitored with caution in the follow-up of childhood cancer survivors." (PMID 38610974, 2024).
chronic hepatitis C (3 papers, 2014 to 2025). "Median and mean log values of cytokines and insulin-like growth factor-1, by chronic hepatitis C virus infection status." (PMID 40700400, 2025). "Unadjusted and adjusted mean differences in log levels of cytokines and insulin-like growth factor-1 between participants with and without chronic hepatitis C virus infection." (PMID 40700400, 2025).
chronic lung disease (3 papers, 2018 to 2023). According to the definitions of the American and British Thoracic Societies, including pulmonary functional tests, X-rays, and CT scans for items such as fibrosis, bronchiectasis, bullae, emphysema, nodular or lymphomatous abnormalities. "For example, acute and chronic lung diseases are associated with an upregulation of IGF1 and IGF1-R." (PMID 34831169, 2021).
chronic myeloid leukemia (3 papers, 2017 to 2019). "This is especially true considering that other multi-target kinase inhibitors, including imatinib, were previously shown to cause growth failure in children affected with chronic myeloid leukemia primarily by perturbing the GH:IGF-1 axis." (PMID 31018508, 2019).
corneal ulcer (3 papers, 2014 to 2025). Area of epithelial tissue loss from corneal surface; associated with inflammatory cells in the cornea and anterior chamber. "The use of Substance P associated with Insulin-like growth factor 1 (IGF-1) has been shown to have a synergistic effect on the epithelization process of corneal ulcers, especially those of neurotrophic origin." (PMID 34287367, 2021). "IGF-1 is different (corneal ulcer healing not affected (application alone)↔corneal neovascularization ↑ ↔ intraocular pressure ↑, and ↑ tendon healing)." (PMID 41471311, 2025).
demyelination (3 papers, 2011 to 2021). "For example, in cuprizone-induced demyelination models, E2 induces production of IGF-1 by astrocytes, which in turn promotes OL proliferation and differentiation." (PMID 33669242, 2021). "Additional studies have shown that insulin-like growth factor-1 (IGF-1) promotes the survival of OPCs during cuprizone-induced demyelination." (PMID 23650566, 2013). "It is likely that this orchestration of repair promoting factors follows a strict pattern since this can also be observed in the lysolecithin model of demyelination, in particular for IGF-1, FGF-2, TGF-ß1." (PMID 21818353, 2011). "Interestingly, constitutive loss of IGF1R impairs OPC survival, proliferation, and subsequent OL remyelination after cuprizone-induced demyelination, again suggesting that IGF-1 plays an important role in OL survival." (PMID 33669242, 2021).
endometrial polyp (3 papers, 2016 to 2024). A benign nodular lesion protruding above the surface of the endometrium. "The aim of the present study was to investigate the relationship between risk of endometrial polyp and genotypes of IGF-1 CA( n) and IGFBP-3 rs2854746 polymorphisms." (PMID 30643822, 2018). "The results suggest that some genotypes of the IGF-1 CA(n) polymorphism have a risk ratio for endometrial polyp." (PMID 30643822, 2018). "The purpose of this study was to examine the association of polymorphisms IGF-1 CA(n) and IGFBP3 rs2854746 with risk of endometrial polyps." (PMID 30643822, 2018). "The underlying mechanisms by which some genotypes of IGF-1 CA(n) polymorphism increases the risk of endometrial polyp was not addressed in our study." (PMID 30643822, 2018). "Furthermore, the disequilibrium between IGF-1 and IGFBP3 levels could be the triggering factor for endometrial polyp development." (PMID 30643822, 2018).
enteropathy (3 papers, 2014 to 2024). "Enteropathy impairs nutrient absorption, increases energy and nutrient losses and causes chronic inflammation that suppresses the growth hormone/IGF1 somatotrophic axis." (PMID 30382849, 2018).
female infertility (3 papers, 2009 to 2023). Diminished or absent ability of a female to achieve conception. "The deletion of insulin receptor substrate-2, a component of the insulin/IGF-1 signalling cascade, causes female infertility through, i.a., disturbances in pituitary functions, leading to reduced numbers of gonadotrophs and decreased LH concentration." (PMID 37880346, 2023). "The FGF21-Tg mice share other phenotypic similarities with long-lived dwarf mice including small size, reduced circulating insulin and IGF-1 concentrations, increased circulating adiponectin levels and female infertility." (PMID 23066506, 2012).
follicular adenomas (3 papers, 2019 to 2022). "Moreover, IGF‐1 and IGF‐1R protein and mRNA expression were significantly higher in follicular adenomas, nodular goiters, and PTC than those in the controls." (PMID 32851683, 2020).
follicular carcinomas (3 papers, 1995 to 2019). "Four of the five follicular carcinomas studied showed a consistent, uniform, strong positivity for IGF-1 mRNA in tumour cells compared with weakly positive surrounding normal follicular tissue and negative stroma." (PMID 7547225, 1995).
Follicular Cyst (3 papers, 2005 to 2024). Cyst due to the occlusion of the duct of a follicle or small gland. "The results showed that the follicular cysts were characterized by significant lower E2, insulin, IGF1 and leptin levels but elevated ACTH and ghrelin levels compared with normal follicles (p < 0.05)." (PMID 37958056, 2023). "Firstly, follicular cyst follicles had extremely significant lower E2, insulin, IGF1 and leptin levels compared with normal follicles (p < 0.01)." (PMID 37958056, 2023).
glucose metabolism disorders (3 papers, 2019 to 2022). "Persistently low IGF-1 concentrations in T2D patients induce glucose metabolism disorders and cytokine destruction, affecting tumor metabolism pathways." (PMID 36553697, 2022). "In another study, IGF-1% upper limit of normal (ULN)/GH ratio was used to assess the effect of glucose metabolism disorders on IGF-1 levels." (PMID 34208601, 2021).
hemangioma (3 papers, 2024 to 2025). A benign vascular lesion characterized by the formation of capillary-sized or cavernous vascular channels. "IGF1 drives both proliferation and adipocyte differentiation of hemangioma stem cells, while IGF2 elevated in proliferative IH, promotes HemSC growth and adipogenesis via upregulation of PPARγ-CEBP axis." (PMID 40978048, 2025). "Our research group previously investigated miR-139-5p and revealed its influence on hemangioma stem cells’ (HemSC) proliferation, migration, and adipogenesis by modulating the IGF-1/IGF-1R pathway." (PMID 38393667, 2024). "Previous studies have confirmed elevated expression of HIF1A, IGF1, and IGF2 in hemangioma tissues." (PMID 40978048, 2025). "The distinct behaviors of IGF1 (showing increased m6A modification but decreased expression during involution) and IGF2 (exhibiting coordinated reduction in both m6A levels and expression) highlight critical aspects of m6A biology in hemangioma progression." (PMID 40978048, 2025).